RBM5 (RNA binding motif protein 5)
Diseases named in the same sentence as RBM5 in open-access papers (continued):
Sharing a sentence is not in itself a finding about the gene and the disease.
breast cancer (13 papers, 2012 to 2024). A primary or metastatic malignant neoplasm involving the breast. "RBM5 encodes a nuclear RNA binding protein that plays a role in the induction of cell cycle arrest and apoptosis and is an apparent tumor-suppressor gene in lung and breast cancer." (PMID 39775235, 2024). "Furthermore, the abnormal expression of RBM5 protein is associated with the occurrence of breast cancer, vestibular schwannoma, and renal cell carcinoma." (PMID 33718153, 2021). "RBM10v2 has a common target greater homology with RBM5 than RBM10v1 and RBM5 as an example of the dichotomous functions of these variants, the RBM5-RBM10v2 complex regulates cell cycle progression and promotes apoptosis, while RBM10v1 inhibits tumor apoptosis in breast cancer." (PMID 33718153, 2021). "Studies have confirmed that RBM5 is downregulated and plays an important regulatory role in various tumors, including breast cancer, prostate cancer, human vestibular schwannoma, and primary lung cancer." (PMID 38201567, 2023). "By contrast, some studies indicated that RBM5 was upregulated in breast cancer and ovarian cancer as a result of overexpression of oncogene EGFR-2." (PMID 33584809, 2020). "Studies have shown a reduced expression of RBM5 in several cancers, including breast cancer, vestibular schwannoma and human non-small cell lung cancer." (PMID 23425895, 2013). "Introduction of RBM5 cDNA into human breast cancer cells deleted of 3p21.3 reduced both anchorage-dependent and -independent cell growth in vitro." (PMID 23158838, 2012). "RBM5 was highly downregulated in breast cancer and prostate cancer." (PMID 33584809, 2020). "RBM5 protein is a negative regulator of cell proliferation: overexpression of the full length LUCA-15/RBM5 in breast cancer CEM-C7 and NSCLC A549 cells suppressed cell proliferation through induction of apoptosis and arrest of tumor cells at the G1 phase of the cell cycle." (PMID 22537942, 2012). "Interestingly, overexpression of RBM5 was also reported to play dual functions in breast cancer." (PMID 32947864, 2020). "One cytotoxic isoform, RBM5 + 5 + 6 t, was downregulated in breast cancer cells (both primary tumors and a cell line) that have overexpressed HER2, which suggested that factors in the EGFR pathway may function as upstream modulators of RBM5 function and/or expression." (PMID 22537942, 2012). "Among all the RBPs (HNRNPU, HNRNPK, RBM5, HNRNPLL, HNRNPH1, HNRNPM, HNRNPA2B1) screened, only SRSF7 (also known as 9G8) was substantially upregulated in hypoxia-treated breast cancer cells." (PMID 34362878, 2021).
lung adenocarcinoma (10 papers, 2012 to 2024). A carcinoma that arises from the lung and is characterized by the presence of malignant glandular epithelial cells. "Lastly, S. enterica expressing the splicing-involved RNA-binding motif protein 5 (RBM5) significantly slowed down tumor growth and metastatic proliferation in a lung adenocarcinoma mice model." (PMID 39443745, 2024). "In this study, we investigated the relationship between RBM5 overexpression and autophagy in human lung adenocarcinoma cells." (PMID 26923134, 2016). "In the present study, we experimentally conducted overexpression of RBM5 in human lung adenocarcinoma A549 cells and for the first time demonstrated that autophagy, aside from apoptosis alone, was also activated by RBM5 overexpression." (PMID 26923134, 2016). "We previously reported that RBM5 overexpression induced apoptosis in human lung adenocarcinoma A549 cells." (PMID 26923134, 2016). "We found that RBM5 significantly inhibited the growth of lung adenocarcinoma in vivo by the induction of apoptosis." (PMID 23721095, 2013). "There is still no effective model in vivo, however, that thoroughly investigates the effect and molecular mechanism of RBM5 on lung adenocarcinoma." (PMID 23721095, 2013). "To assess the expression of RBM5 mRNA and protein in human lung adenocarcinoma, we performed RT-PCR and Western blot analysis on 30 pairs of primary lung tumor versus adjacent non-tumor tissues." (PMID 22866867, 2012). "Overexpression of RBM5 is reported to induce autophagy in human lung adenocarcinoma cells." (PMID 35004299, 2021). "Besides, RBM5 can be acted as a tumor suppressor, and it inhibits the formation of lung adenocarcinoma through several apoptotic signaling pathways." (PMID 33000861, 2020). "Considering the similarities between RBM5 and RBM10, and the recent finding that RBM10 is mutated in up to 21% of invasive lung adenocarcinomas, we hypothesized that RBM10 shares RBM5’s tumor-suppressor properties in SCLC." (PMID 28662214, 2017). "Our findings showed for the first time that RBM5 overexpression induced autophagy in human lung adenocarcinoma cells, which might be driven by upregulation of Beclin1, NF-κB/P65, and downregulation of Bcl-2." (PMID 26923134, 2016). "Herein, we hypothesized that inhibition of EGFR in lung adenocarcinomas might be achieved via RBM5 overexpression." (PMID 25441176, 2014). "In this study, we examined the RBM5 expression on 30 samples of lung adenocarcinoma patients in the hope to better understand the role and function of this cancer suppressor in the fostering and growing of lung adenocarcinoma." (PMID 22866867, 2012). "Here, we demonstrate that overexpression of RBM5 suppressed EGFR expression, both in lung adenocarcinoma cell line A549 cells and in A549 xenograft tumors." (PMID 25441176, 2014). "In our current study, we found that the expression of RBM5 mRNA and protein were both significantly reduced in 120 cases of surgically resected NSCLC compared to the adjacent normal tissues, 30 of which were lung adenocarcinoma." (PMID 23721095, 2013). "Afterwards, we inhibited EGFR expression in the lung adenocarcinoma cell line NCI-H1975 using small interfering RNA, and found that RBM5 expression was not directly regulated by EGFR in non-smoker-related lung adenocarcinomas." (PMID 25441176, 2014). "Our result confirms the previous finding that RBM5 expression was decreased in human lung adenocarcinoma tissues compared to that in the corresponding non-tumor tissues." (PMID 22866867, 2012).
prostate carcinoma (6 papers, 2012 to 2021). A carcinoma that arises from epithelial cells of the prostate gland. "We found that miR-483-5p expression is significantly upregulated in prostate cancer cell lines and is negatively associated with RBM5 protein levels." (PMID 28727371, 2017). "The present study describes a potential mechanism underlying a miR-483-5p/RBM5 link that contributes to prostate cancer development." (PMID 28727371, 2017). "Mitochondrial apoptotic activity is significantly increased when RBM5 is overexpressed in prostate cancer cells." (PMID 34804951, 2021). "Our study describes the regulatory link between miR-483-5p and RBM5 and identifies a potential mechanism of RBM5 dysregulation and its contribution to prostate cancer progression." (PMID 28727371, 2017). "Our results suggested that miR-483-5p plays a critical role in cell proliferation and invasion by regulating its target gene RBM5 in human prostate cancer." (PMID 28727371, 2017). "In summary, the present study is the first to suggest the potential prognostic significance of miR-483-5p mediated the downregulation of RBM5 expression that promotes cancer cell proliferation and invasion in prostate cancer." (PMID 28727371, 2017). "miR-483-5p suppression inhibits prostate cancer cell growth and invasion by directly targeting RBM5." (PMID 28727371, 2017). "Overexpression of RBM5 inhibited growth of human prostate cancer while it was demonstrated to be downregulated in serous ovarian carcinoma." (PMID 28061901, 2017). "In another study, expression of cleaved caspase-9 and cleaved caspase-3 was upregulated by RBM5 in prostate cancer." (PMID 28061901, 2017). "In this study, we investigated the role of miR-483-5p in prostate cancer and examined RBM5 regulation by miR-483-5p." (PMID 28727371, 2017). "Enforced RBM5 expression alleviated miR-483-5p promotion of prostate cancer cell growth and invasion in LNCaP cells." (PMID 28727371, 2017). "Our research revealed that overexpression of RBM5 induced the apoptosis of prostate cancer PC-3 cells by promoting the mitochondrial apoptotic pathway, activating the caspase-9- and caspase-3-dependent apoptosis." (PMID 23158838, 2012). "We first analyzed the expression of RBM5 by IHC staining in a collection of prostate cancer and normal tissues in a Chinese cohort." (PMID 23158838, 2012). "In order to explore the role of RBM5 in prostate cancer, we transfected pcDNA3.1-RBM5 vector into human prostate cancer PC-3 cells, and confirmed the overexpression of RBM5 RNA and protein by RT-PCR and western blot." (PMID 23158838, 2012). "The RBM5 protein was virtually undetectable in prostate cancer but highly expressed in normal prostatic tissue." (PMID 23158838, 2012). "The aim of this study is to investigate the expression of RBM5 in human prostate cancer and its mechanism of tumor suppression." (PMID 23158838, 2012). "The expression of RBM5 protein was significantly decreased in cancerous prostatic tissues, which suggests that RBM5 plays an important role in the pathogenesis of prostate cancer." (PMID 23158838, 2012). "In this study, we first examined RBM5 protein expression in prostate cancer tissue and normal prostate tissue with immunohistochemistry staining." (PMID 23158838, 2012). "This implies a correlation between prostate cancer and the expression of RBM5 and further suggests that RBM5 plays a critical role in the occurrence and development in prostate cancer." (PMID 23158838, 2012). "We next investigated the role of RBM5 in prostate cancer progression." (PMID 28727371, 2017). "There results suggested that RBM5 inhibits prostate cancer cell growth and invasion." (PMID 28727371, 2017). "RBM5 overexpression inhibited prostate cancer cell growth and invasion in LNCaP cells." (PMID 28727371, 2017).
prostate carcinoma (continued). "To determine whether miR-483-5p targeting of RBM5 was required for inhibiting prostate cancer cell proliferation and invasion, we employed an expression construct that encodes the entire RBM5 coding sequence but lacks the 3′-UTR." (PMID 28727371, 2017). "RBM5 may induce the apoptosis of prostate cancer PC-3 cells by modulating the mitochondrial apoptotic pathway, and thus RBM5 might be a promising target for gene therapy on prostate cancer." (PMID 23158838, 2012). "In this study, we employed PC-3 cells to investigate the function of RBM5 in prostate cancer cells." (PMID 23158838, 2012). "In summary, we have shown that RBM5 has a correlation with prostate cancer." (PMID 23158838, 2012). "Overall, RBM5 was expressed in 10 of 11 (90.9%) normal prostate tissues, and the cytoplasmic/nuclear ratio of the staining was about 50%; while the RBM5 was expressed in two of 12 prostate cancer specimens (16.7%), and the cytoplasmic/nuclear ratio of the staining was about 10%." (PMID 23158838, 2012). "In this study, we hypothesized that RBM5 may be involved in human prostate cancer cells." (PMID 23158838, 2012). "However, the role of RBM5 in prostate cancer has yet to be elucidated." (PMID 23158838, 2012). "The ectopic introduction of RBM5 can induce the apoptosis of human prostate cancer PC-3 cells by modulating the mitochondrial apoptotic pathway, and thus RBM5 may be a promising target for gene therapy on prostate cancer." (PMID 23158838, 2012). "But whether the expression levels of RBM5 have changes in prostate cancer had not been reported." (PMID 23158838, 2012).
bladder cancer (5 papers, 2021 to 2024). "RBM5 is downregulated in bladder cancer, and its overexpression promotes apoptosis and inhibits tumor growth." (PMID 39132499, 2024). "Previous studies have demonstrated that downregulated RBM5 promotes the progression of bladder cancer." (PMID 38201567, 2023). "Downregulated RNA-binding motif protein 5 (RBM5) promotes the development and progression of various tumors, including bladder cancer (BC)." (PMID 38201567, 2023). "For instance, the up-regulated hsa-miR-432-5p targets RNA-binding motif protein 5 and regulate apoptosis in bladder cancer cells." (PMID 35264666, 2022). "Similarly, down-regulation of RBM5 in bladder cancer cells leads to inhibition of apoptosis by increasing the expression of β-catenin-mediated mir-432-5p." (PMID 34804951, 2021). "The down-regulation of RBM5 activates β-catenin, which binds to the T-cell factor/lymphocyte enhancer factor element of the miR-432-5p promoter and elevates the expression of miR-432-5p in bladder cancer cells." (PMID 34804951, 2021). "Several RBM proteins have been studied in the context of bladder cancer, including RBM3, RBM10, RBM24, RBM5, and RBMX." (PMID 39132499, 2024).
glioma (4 papers, 2017 to 2021). A benign or malignant brain and spinal cord tumor that arises from glial cells (astrocytes, oligodendrocytes, ependymal cells). "In this study, we demonstrated that Bcl-2 was downregulated while the level of Bax, cleaved caspase-3, and TNF-α was increased significantly by RBM5 in gliomas cells, which suggest that RBM5, at least partly, promoted cell apoptosis in gliomas cells." (PMID 28061901, 2017). "Accordingly, our data proved that RBM5 promoted tumorigenesis of gliomas through activation of Wnt/β-catenin signaling and increased cell apoptosis." (PMID 28061901, 2017). "And we showed that RBM5 played a suppressor role in gliomas by inhibiting canonical Wnt signaling and enhancing apoptosis." (PMID 28061901, 2017). "In this study, we found RBM5 was decreased in gliomas tissue samples and clinically correlated with poor prognosis in gliomas." (PMID 28061901, 2017). "In a recent study RNA-binding motif protein 5 (RBM5) was demonstrated showing a suppressor role in gliomas by inhibiting Wnt/β-catenin signaling and inducing cell apoptosis." (PMID 28978116, 2017). "But on the whole, our data suggested that RBM5 suppressed both migration and invasion of human gliomas cells." (PMID 28061901, 2017). "Our data suggest that RBM5 plays a suppressor role in gliomas and provide a new promising therapeutic target for patients with gliomas." (PMID 28061901, 2017). "Our data demonstrated that upregulated RBM5 significantly inhibited cell growth and disrupted DNA synthesis in gliomas cells." (PMID 28061901, 2017). "Further, both migration ability and invasive capacity of gliomas cells were markedly suppressed by RBM5 overexpression." (PMID 28061901, 2017). "The mRNA level of RBM5 was determined in gliomas tissues and cell lines by real-time quantitative PCR (qRT-PCR) assay while the association of RBM5 expression with prognosis was analyzed by Kaplan-Meier method and compared by log-rank test." (PMID 28061901, 2017). "Accordingly, we determined the effect of RBM5 overexpression on migration and invasiveness of gliomas cells." (PMID 28061901, 2017). "RBM5 plays a suppressor role in human gliomas by inhibiting Wnt/β-catenin signaling and inducing cell apoptosis." (PMID 28061901, 2017). "In summary, RBM5 was downregulated in gliomas and disrupted both proliferation and migration ability of gliomas cells by activating Wnt/β-catenin signaling and inducing cell apoptosis." (PMID 28061901, 2017). "And decreased RBM5 expression was clinically correlated with tumor stage, patient age, and poor prognosis of gliomas patients." (PMID 28061901, 2017). "To investigate the role of RBM5 in gliomas, we successfully constructed a gliomas cell line stably expressing RBM5 with lentivirus vector." (PMID 28061901, 2017). "Additionally, that apoptotic rate increased significantly from less than 1 to 32% in RBM5-overexpressed SHG44 cells further supported the pro-apoptosis role of RBM5 in gliomas cells." (PMID 28061901, 2017). "But how did RBM5 suppress oncogenesis and metastasis in gliomas?" (PMID 28061901, 2017). "Consistently, RBM5 was shown to be weakly expressed in either gliomas tissues or cell lines here." (PMID 28061901, 2017). "So, our data suggest that RBM5 could simultaneously inhibit Wnt/β-catenin signaling and activate apoptosis in human gliomas cells." (PMID 28061901, 2017). "However, different with the early reports, we found in this study that Wnt/β-catenin signaling was activated by RBM5 in gliomas cells." (PMID 28061901, 2017). "Based on these facts, we concluded that RBM5 played a suppressor role in gliomas." (PMID 28061901, 2017). "RBM5 was shown to be downregulated in gliomas tissues and gliomas cell lines." (PMID 28061901, 2017). "Our data indicate that RBM5 may function as a suppressor in gliomas." (PMID 28061901, 2017). "Also, RBM5 was expressed weakly in three gliomas cells including U87, U251, and SHG44." (PMID 28061901, 2017).
glioma (continued). "However, there was no report about the role of RBM5 in gliomas." (PMID 28061901, 2017).
non-small cell lung carcinoma (4 papers, 2012 to 2022). A group of at least three distinct histological types of lung cancer, including non-small cell squamous cell carcinoma, adenocarcinoma, and large cell carcinoma. "Our previous studies suggested that RBM5 expression was negatively correlated with the expression of epidermal growth factor receptor (EGFR) in non-small cell lung cancer (NSCLC) tissues." (PMID 25441176, 2014).
small cell lung carcinoma (4 papers, 2007 to 2021). Small cell lung cancer (SCLC) is a highly aggressive malignant neoplasm, accounting for 10-15% of lung cancer cases, characterized byrapid growth, and early metastasis. "The decrease of RBM5 expression may be a key step in the development of small cell lung cancer, because RBM5 regulates many transformation related processes in small cell lung cancer cells." (PMID 33718153, 2021).
Azoospermia (3 papers, 2013 to 2022). Absence of any measurable level of sperm,whereby spermatozoa cannot be observed even after centrifugation of the semen pellet. "Mice with a homozygous ENU-induced allele point mutation in RBM5 present with azoospermia and germ cell development arrest at round spermatids." (PMID 35013161, 2022). "Another study revealed that a missense mutation (R263P) in the second RRM of RNA binding motif protein 5 (Rbm5) affected pre-mRNA splicing, produced aberrantly spliced transcripts and displayed spermatid differentiation arrest, azoospermia and male sterility." (PMID 31892844, 2020). "Mice carrying a missense mutation (R263P) in the second RNA recognition motif (RRM) of RBM5 exhibited spermatid differentiation arrest, germ cell sloughing and apoptosis, which ultimately led to azoospermia (no sperm in the ejaculate) and male sterility." (PMID 23935508, 2013).
gastric cancer (3 papers, 2016 to 2022). A primary or metastatic malignant neoplasm involving the stomach. "The activities of RBM5 and USP15 were also significantly activated in gastric cancer." (PMID 26897165, 2016).